TNF (tumor necrosis factor)
Diseases named in the same sentence as TNF in open-access papers (continued):
Sharing a sentence is not in itself a finding about the gene and the disease.
ischemia (continued). "The inflammatory cytokines rising in COPD, such as IL-6, C-reactive protein and TNF-α, would also lead to ischemia, which further implies that inflammation can trigger pulmonary hypertension by changing the blood vessels of the pulmonary cycle." (PMID 33108241, 2020). "Especially IL- 1β, IL-6 and TNF-α play a primary role in hippocampus inflammation responding to transient global ischemia/reperfusion." (PMID 32150581, 2020). "Concomitantly, immunohistochemistry demonstrated that macrophages in the subcapsular sinus in deep and superficial CLNs increased TNF-α expression after focal ischemia, this response was suppressed by MAZ treatment." (PMID 31757960, 2019). "In general, M had higher ipsilateral cortical levels of TNFα pro-inflammatory cytokine at three days post-ischemia compared with F (n = 5 per group)." (PMID 31382688, 2019). "Nevertheless, attempts to both neutralize and stimulate TNF-α in post-myocardial infarction patients during ischemia and reperfusion have resulted in worsening the condition of the heart." (PMID 31614478, 2019). "After ischemia, astrocytes, microglia, and MDMs play important roles during rehabilitation with the modulation of cytokines or chemokines, such as TNF-α and IL-1." (PMID 31031649, 2019). "Electroacupuncture is also reported as a safe and effective therapy to attenuate the overactivation of Iba-1 and ED1 positive microglia and the expression of TNF-α, IL-1β, and IL-6 and leads to reduced neurological and sensorimotor impairment in ischemia." (PMID 31031649, 2019). "TNF-α is related to excitotoxic and neuroinflammatory processes that occur in neurodegenerative disease such as ischemia and traumatic brain injury." (PMID 32257907, 2019). "Astrocytes activated by ischemia and anoxia secrete many pro- and anti-inflammatory factors, such as IL-1β, IL-6, TNF-α, TGF-β, VEGF-A, MCP-1 CXCL-1, MMP-2, and MMP-9, which influence BBB integrity." (PMID 31779652, 2019). "In particular, TNF-α, as a key inflammatory mediator, is reported to have a paradoxical effect including both protecting and detrimental roles in ischemia-induced heart dysfunction." (PMID 31344138, 2019). "In our hands, ischemia appeared to lead to a prolonged augmentation of TNF-α in wounds on day 6 and day 9 after wounding though this was not significant." (PMID 30650075, 2019). "Several authors have described that post-ischemic TNFα neutralization significantly reduces the infarct volume in both transient and permanent ischemia models." (PMID 31544811, 2019). "In adult ischemia, TNF-α is decreased with glucocorticoid agonism and is connected to increased apoptosis." (PMID 31315247, 2019). "When there are certain stimuli, such as ischemia or hemorrhage, TNF-α is synthesized and released by astrocytes, microglia, or neurons in response to the stimuli and is involved in many pathophysiological processes of ischemic stroke or ICH." (PMID 31031649, 2019). "A growing body of evidences also suggests that MEK/ERK pathways are responsible for the elevated level of TNF-α, IL-1β, IL-6, and iNOS following ischemia, which further highlights their neuroinflammatory role." (PMID 31049133, 2019). "In contrast, the group of Gugiyama reported the deleterious impact of a TNFα-cPLA2 cardiac signaling in a model of ischemia-reperfusion." (PMID 30988334, 2019). "Gene expression of inflammatory mediators, monocyte chemoattractant protein 1 (MCP1), tumor necrosis factor (TNF)-α and interleukin (IL)-6, by real-time PCR also showed an ischemia time-dependent increase in the ischemic kidneys at the early stage of AKI." (PMID 30873045, 2019). "Our results show that TNF-α, IL-6, and IL-1 are increased in the left ventricle undergoing ischemia for 14 days, thereby increasing the damage." (PMID 30642049, 2019).
ischemia (continued). "Based on the result of the current study, lower superoxide dismutase (SOD) and glutathione (GSH) (P<0.05) and higher malondialdehyde (MDA) and TNF-α levels were observed in the ischemia group than those of the sham group (P<0.01)." (PMID 31231488, 2019). "The numbers of TNF-α single-positive and TNF-α+/Ly6C+ double-positive cells were 31 ± 7.87 and 1.0 ± 1.73 per view field in the ischemia vehicle group, and the proportion of Ly6C+ cells coexpressing TNF-α was 0.9 ± 1.2%." (PMID 30405724, 2018). "Previous studies have shown that COX inhibitors are able to suppress TNF-α, IL-6, and IL-1β in renal tissue after ischemia." (PMID 29535870, 2018). "Microglia secrete pro-inflammatory cytokines, like IL-1β and TNF-α, after being stimulated by ischemia or infection." (PMID 29665808, 2018). "We examined TNF-α reactivity in Ly6C+ cells in the ischemia vehicle group and in the ischemia + MSC group." (PMID 30405724, 2018). "Our data demonstrated that the concentrations of IL-1β (6, 24, and 72 h after reperfusion) and TNF-α (6 and 24 h after reperfusion) in serum were significantly enhanced after ischemia." (PMID 29540536, 2018). "BDNF can suppress TNF-α and its mRNA expression, this exacerbating ischemia-induced injury, while it increases IL-10 and its mRNA expression, which play an anti-inflammatory neuroprotective role." (PMID 30622436, 2018). "It has been suggested that pro-inflammatory cytokines including TNF-α and IL-1 play a pivotal role in the pathology of ischemia/reperfusion-induced brain injury." (PMID 30029514, 2018). "By 14 days post-ischemia, TNFα and IL-1β levels tended to come back down, whereas the expression of IGF-1 were increased, similar to our astrocyte-activated microglial cultures." (PMID 29764475, 2018). "Recently, baicalin was found to effectively downregulate the expression of NOD2 receptor and TNF-α in neurons suffered ischemia-reperfusion injury and inhibit activation of NLRP3 inflammasome in macrophages." (PMID 30647760, 2018). "For instance, brain slice studies have shown that ischemia, which upregulates the expression of cytokines such as IL-1β and TNF-α, induces Cx43 dephosphorylation." (PMID 29587860, 2018). "The proportion of Ly6C+ cells coexpressing TNF-α was significantly increased (19.67 ± 6.54%) vs. the ischemia vehicle group (0.9 ± 2.2%, p < 0.01)." (PMID 30405724, 2018). "It has been shown that up-regulation of TNF-alpha/NF-kB signaling pathway after ischemia and reperfusion induces inflammation and tissue injury by the activated neutrophils." (PMID 30555831, 2018). "Paradoxically, investigators also reported that treatment with 15‐deoxy‐Δ12,14‐PGJ2 decreases TNF‐α production in cardiomyocytes and reduces myocardial damage of ischemia/reperfusion." (PMID 29335338, 2018). "Administration of the H4R antagonist, JNJ, reduced TNF-α and IL-1β assayed in the peripheral plasma 7 days after ischemia." (PMID 30420807, 2018). "Tumor Necrosis Factor α (TNFα) is a pro-inflammatory cytokine whose upregulation is a key marker of the acute inflammatory phase in several pathophysiologic states including ischemia, myocarditis, and cardiomyopathies." (PMID 28588504, 2017). "At day 14 post‐ischemia, the levels of IL‐6 and TNF‐α in the exercise‐treatment group remained significantly lower than ischemia group." (PMID 29201553, 2017). "During infectious processes, trauma, or ischemia, IL-1 and TNF-α production synergistically lead to the cascaded activation of inflammatory mediators." (PMID 28773202, 2017). "Activated macrophages secrete TNFα and cathepsin L, which stimulate further production and activation of heparanase by these cells and by ischemia-induced renal injured cells." (PMID 28388547, 2017). "Evidently, exercise training induces a long-term low rating increment in the concentration of TNF-α, eventually creating neuronal resistance and defense against the ischemia and reperfusion injuries." (PMID 28446953, 2017).
ischemia (continued). "EA at Zusanli also has the potential to reduce serum TNF level in septic rats, protect intestinal barrier integrity from ischemia injury, and reduce postoperative local inflammatory response to alleviate adhesion formation in rats." (PMID 29333186, 2017). "Low dose of TNF-α improves myocardial function while high dose of TNF-α increases myocardial injury following ischemia and reperfusion." (PMID 28460644, 2017). "The expressions of the TNF-α and IL-1β proteins were significantly higher in the ischemia group, compared to the sham-operated group (P<0.05)." (PMID 27533766, 2016). "Administration of SQ29548 inhibited microglia/macrophages activation and enrichment, including both M1 and M2 phenotypes, and attenuated ischemia-induced IL-1ß, IL-6, and TNF-α up-regulation and iNOS release." (PMID 27775054, 2016). "Etanercept, a commercially available TNF-α inhibitor, showed a significant protective effect against axonal damage after induction of acute ischemia in in vivo rat models." (PMID 27259948, 2016). "According to some reports, IL-1β and TNF-α expression begin to increase between 4 and 6 h after the onset of ischemia." (PMID 27544687, 2016). "Some studies have indicated an anti-apoptotic role of Sfrp2 in mediating cellular resistance to UV, TNF, or ischemia-induced apoptosis in mammalian cell lines." (PMID 27048460, 2016). "The LXW7 group exhibited lower expressions of TNF-α and IL-1β, compared to the ischemia group (P<0.05)." (PMID 27533766, 2016). "In our real-time PCR experiments, though, we already observed robust increases of both IL-1β and TNF-α expression at 4 h of permanent MCAO induced ischemia." (PMID 27544687, 2016). "Because the cytokines, TNF-α and IL-1β are the most important pro-inflammatory mediators after the onset of ischemia." (PMID 27716383, 2016). "Another member of this family, miR-181c, was identified as directly targeting tumor necrosis factor-alpha (TNF-α) following ischemia, thereby regulating microglial activation and microglial-mediated neuronal injury." (PMID 27777645, 2016). "Previous studies have shown increased TNF-α production in in vitro and in vivo ischemia models and have demonstrated that neutralization of TNF-α by intravitreal TNF-α antibody injection significantly preserves retinal function." (PMID 27259948, 2016). "TNF-α concentration in the reperfusion group was much higher than that of the ischemia and sham groups (8.90 ± 1.43 vs. 6.28 ± 0.94 pg/mL, P < 0.05 and 8.90 ± 1.43 vs. 5.44 ± 1.58 pg/mL, P < 0.05, respectively)." (PMID 25677043, 2015). "Production and release of TNF increase following elevated IOP or ischemia, suggesting TNF as an attractive therapeutic target." (PMID 25873768, 2015). "Cardiocytes also produce TNF-α in response to ischemia, and TNF-α plays a critical role in the myocardial dysfunction that arises after acute injury." (PMID 26491537, 2015). "To understand the synergistic effect of geniposide and ginsenoside Rg1 on TNF-α and TGF-β expression pattern in ischemia-activated microglia, we clarified the distribution of genes in TNF-α and TGF-β pathways by cluster analysis." (PMID 26693244, 2015). "Compared with the sham surgery group, the TNF-α, IL-1β and IL-6 serum levels in the rats were significantly elevated in the ischemia group (P<0.01)." (PMID 25667680, 2015). "And there is more TNF-α and IL-1 expression in the diabetes ischemia group than that of standard ischemia group with normal level of blood sugar (P < 0.05) in both 24 hours and seven days after reperfusion." (PMID 26844229, 2015). "We have previously shown that recombinant TNFα has a dual effect on myocardial function after ischemia." (PMID 26430494, 2015). "bFGF was found to down-regulate the expression of TNF-α and IL-1 following ischemia and reperfusion, which contributed to alleviating brain injury." (PMID 26729092, 2015).
ischemia (continued). "Induction of cerebral ischemia increased TNF-α mRNA expression levels significantly at 4 and 24 h, following ischemia in the left ischemic hemispheres in the hypoxia group compared with those in the control (P=0.002 for 4 and 24 h)." (PMID 24520277, 2014). "Remarkably, the two drugs in combination cumulatively decreased the infarct size in the cerebrum and diminished the ischemia-induced inflammatory mediators being most pronounced for TNF-α expression." (PMID 25416145, 2014). "The subsequent reduction of the generation of superoxide anions and peroxides upon sudden reperfusion following ischemia, attenuating lipid oxidation, reducing the levels of NF-κB and TNF-α, inflammatory response, and cellular apoptosis, as well as renal IRI." (PMID 25322861, 2014). "In MCAO rats killed at 7 days, iNOS and TNF-α immunofluorescence that was augmented following ischemia was attenuated with E, SH or E + SH treatment." (PMID 25416145, 2014). "In the current study, the early increase in urinary TNF-α likely resulted from the direct action of CsA on resident renal cells or from tubular cells that suffered ischemia due to CsA-induced pre-glomerular vasoconstriction." (PMID 25072153, 2014). "Our findings revealed that DHI treatment significantly suppressed the expression of proinflammatory cytokines TNF-α and IL-1β levels after ischemia." (PMID 24707308, 2014). "In the present study, we demonstrated that the ischemia-induced up-regulation of iNOS, IL-1β, IL-6 and TNF-α was inhibited by treatment with GL." (PMID 24594628, 2014). "Tumor necrosis factor-α (TNF-α) is an important inflammatory factor and its expression levels markedly increase in the brain following ischemia." (PMID 25371754, 2014). "Other studies confirmed also that inflammatory mediators, such as IL-1β and TNFα, are important contributors to CNS neural tissue damage induced by ischemia." (PMID 24324296, 2013). "Taken together, here, for the first time, we investigated the potential effects of Nec-1 on ischemia-injury in vitro cultured NRK-52E cells with TNF-α stimulation and ATP depletion." (PMID 24351845, 2013). "The expression level of soluble TNF-α (17 kDa) in the murine retina was significantly increased 24 h after the onset of ischemia in comparison to the control group." (PMID 25505560, 2013). "During ischemia, cytokines, such as TNF-α, IL-1β, IL-6, and chemokines such as cytokine-induced neutrophil chemoattractant (CINC) and MCP-1 are produced by a variety of activated cell types, including endothelial cells, microglia, astrocytes and neurons." (PMID 23663236, 2013). "In the present study, MCAO-induced ischemia and reperfusion resulted in 1.23-fold elevation in the expression of TNF-α in the brain tissues." (PMID 24285977, 2013). "Neuronal production of TNF-α in the rodent brain has been reported following ischemia and isoflurane anesthesia." (PMID 23922745, 2013). "A growing body of evidence indicates that the inflammatory response, associated with pro-inflammatory cytokines IL-1β, TNF-α and chemotactic cytokine MCP-1, plays a major role in renal dysfunction following ischemia and reperfusion." (PMID 23759023, 2013). "Effects of active linaclotide on repair of barrier and cell function in pig jejunum after ischemia and in T84 cells after treatment with proinflammatory cytokines, interferon-γ and tumor necrosis factor-α were examined." (PMID 22553939, 2012). "TNF-α is a key pro-inflammatory cytokine that has been reported to play an important role in the events that follow ischemia." (PMID 22950459, 2012). "It has been reported that levels of TNF-α in the heart are increased within 15 min of ischemia, whereas TNF-α mRNA levels increase even earlier and persist in cardiomyocytes with time." (PMID 23189120, 2012).
ischemia (continued). "In contrast, others have shown that an increase in circulating TNF-α by treatment with either TNF-α or lipopolysaccharide before the onset of the ischemia has a beneficial effect in the ischemic brain and mediates the development of ischemic tolerance." (PMID 22394384, 2012). "Anti-inflammatory properties of PTX include the inhibition of TNF-alpha production which is expressed in brain after ischemia." (PMID 23493977, 2012). "It is demonstrated that hypoxia-inducible factor-1α (HIF-1α), interleukin-1 β (IL-1β) and tumor necrosis factor α (TNF-α) expression increase in the rat brain during cerebral ischemia induced by different models of ischemia." (PMID 23351182, 2012). "Increased TNF-α has been observed in other experimental models such as those for ionizing radiation and ischemia." (PMID 21711488, 2011). "Angiotensin II, catecholamines, tumor necrosis factor-alpha (TNF-alpha) and ischemia induce generation of ROS in the myocardium." (PMID 26791643, 2011). "The comparison between patients with intermittent claudication, with either ischemia or critical ischemia, and a control group revealed that TNF-α and IL-1 receptors were more significant markers than the cytokines themselves." (PMID 21875436, 2011). "During ischemia, cytokines, such as TNF-α, IL-1β, IL-6, and chemokines such as CINC and MCP-1 are produced by a variety of activated cell types, including endothelial cells, microglia, astrocytes and neurons." (PMID 22196138, 2011). "At the same time-point, the expression of TNF-α in the ischemia zone was greater than that in the border zone, and little in the non-ischemia zone." (PMID 21584281, 2011). "Stress-induced proinflammatory cytokines, particularly TNF-α and IL-1β synthesized and released in response to the stress of global ischemia accompanying CA, play a pivotal role in development of postresuscitation ventricular dysfunction." (PMID 22011328, 2011). "Both TNF-α mRNA and protein expression have been shown to be increased in the retina following ischemia." (PMID 21152396, 2010). "Development of ischemia was demonstrated by changes in the CSF concentration of interleukin 6 (IL-6), tumor necrosis factor alpha (TNFa) and lactate, which are considered to increase when CNS ischemia ensues." (PMID 20230612, 2010). "In light of the recent finding that microglia protect neurons from ischemia via a TNF-mediated mechanism, this approach has the potential to stimulate a positive outcome via two separate mechanisms." (PMID 21134289, 2010). "TNF-α, as an important proinflammatory cytokine, appears to exacerbate cerebral injury of ischemia while IL-10, an anti-inflammatory cytokine, ameliorates ischemic insult of brain." (PMID 21490702, 2010). "Consistent with our study, previous studies have suggested that systematic treatment with thalidomide suppresses spinal TNF-α expression during neuropathic pain and spinal cord ischemia/reperfusion injury." (PMID 20923560, 2010). "In the two ischemia groups our measurements indicated an mRNA up-regulation of TNF-α, IL-1β, and IL-6 that was unaffected by COX-2 enzyme blockage." (PMID 17150094, 2006). "In the initial stages of ischemia, neural and glial cells in the brain are activated by the lack of blood flow and oxygen, leading to the release of inflammatory mediators such as tumor necrosis factor-alpha (TNF-α), interleukin-1 beta (IL-1β), and interleukin-6 (IL-6)." (PMID 40421420, 2025). "Additionally, the E-MSC-treated ischemia groups showed a substantial reduction in inflammatory cytokine (TNF-α, IL-1β, IL-6, and TGF-β) levels and a notable increase in angiogenetic cytokine (ANG1, FGF, VEGF, and PDGF) levels compared to the control group." (PMID 40595285, 2025). "Within 24 h of the onset of ischemia, brain tissues exhibit a substantial inflammatory response, accompanied by a significant escalation in pro-inflammatory cytokine levels, such as IL-1β and TNF-α, which further exacerbate brain injury." (PMID 40260076, 2025).